BRAF (B-Raf proto-oncogene, serine/threonine kinase)
Diseases named in the same sentence as BRAF in open-access papers (continued):
Sharing a sentence is not in itself a finding about the gene and the disease.
melanoma (continued). "Since BRAF inhibitors may induce increased PD-L1 expression in tumor cells and help restore the immune-stimulating microenvironment of BRAF-mutant melanoma, the combination of BRAF inhibitors and ICIs may provide a stronger antitumor effect." (PMID 34249711, 2021). "GPNMB is related to mutations in BRAF and MEK that do cause melanoma." (PMID 34570764, 2021). "Hence, in advanced BRAF(V600E) melanoma, the standard of care is the combination of BRAF and MEK inhibitors (dabrafenib and trametinib)." (PMID 33672955, 2021). "In this study, we developed novel experimental and computational methods to track thousands of single melanoma cells continuously over the first 4 days of treatment with the BRAF inhibitor dabrafenib and uncovered a striking degree of heterogeneity in drug response." (PMID 33741929, 2021). "The contrasting results of V600 mutant specific inhibitors in thyroid cancer compared to melanoma and hairy cell leukemia could be due to different response and resistance mechanisms to BRAF inhibition dependent on cell types." (PMID 34630336, 2021). "Therapy with an antibody directed against PD-1 with or without the addition of ipilimumab is the standard therapy at least for advanced melanoma without BRAF mutation." (PMID 33993415, 2021). "However, current therapies including BRAF/MEK targeted therapies or immunotherapies only benefit a subset of melanoma patients due to the emergence of intrinsic or extrinsic resistance mechanisms." (PMID 34771678, 2021). "In November 2008, a 35-year-old man was diagnosed with melanoma on the left cervical region (Breslow thickness 1.2 mm, not ulcerated, negative neck sentinel node; pT2a, positive for the BRAF V600E mutation)." (PMID 34136385, 2021). "Other studies showed that six out of 16 melanoma tumors acquired EGFR expression after the development of resistance to BRAF or MEK inhibitors, and acquired resistance was found with the overexpression of signaling receptors like EGFR, PDGFRβ, or MET that reactivation the MAPK pathway." (PMID 34360915, 2021). "Oncogenic BRAF/mitogen-activated protein kinase kinases (MKK)/ERK signaling in melanoma cells modulates a network of miRNAs, by means of downregulation (let-7i, miR-22, -34a/b, -125a, -132, -211) or upregulation (miR-17-5p, -20a, -92b, -106a/b, -221/222) of miRNA expression." (PMID 34123788, 2021). "In melanomas harbouring the BRAFV600E mutation, the most common BRAF mutation, the BRAF kinase, is constitutively activated and thus signalling through the BRAF-MEK-ERK cascade is hyperactivated and always turned on, which can result in uncontrolled cell proliferation." (PMID 34621046, 2021). "The combination of targeted therapy and immunotherapy in melanoma has progressed in recent decades, including BRAF inhibitors and BRAF/MEK combination therapy and CTLA-4 and PD-1 inhibitors, whose efficacy in advanced stages of melanoma has been demonstrated in randomized trials." (PMID 35186949, 2021). "Likewise, BRAF-mutated melanoma cell lines growing under 3D conditions and enriched in CICs overexpressed SCD1, exhibited resistance to BRAF and MEK inhibitors." (PMID 34429143, 2021). "Therefore, the diagnostic value of PLA1A in BRAF and NRAS-mutated samples of melanoma patients was investigated to confirm the diagnostic utility of PLA1A during melanomagenesis." (PMID 33723350, 2021). "Thus, we and others assessed the safety and efficacy of a short course of vemurafenib (an oral BRAF inhibitor clinically effective in BRAF-V600E + melanoma) delivered to 50 evaluable relapsed/refractory HCL patients enrolled in two phase-2 clinical trials." (PMID 33731847, 2021). "Moreover, melanoma cells resistant to BRAF inhibitors have a MEK-independent survival driver that can be blocked by inhibitors of the PI3K pathway." (PMID 34680615, 2021).
melanoma (continued). "According to the result from the phase III METRIC trial, trametinib single-agent treatment obtained an ORR of 22% and a median PFS of 4.8 months, which was not as ideal as that of BRAF-targeted therapy in melanoma harboring BRAF mutation." (PMID 34924562, 2021). "Even though our results suggest that the NECTIN4-targeting ADCs, such as enfortumab vedotin, exert antitumor effects against melanoma regardless of their BRAF mutation status, even after the melanoma cells develop to acquire BRAFi resistance." (PMID 33478111, 2021). "Studies have shown that BRAF-targeted kinase inhibitors are effective for patients with BRAF gene mutations, and the combined use of BRAF and MEK inhibitors has been approved for the treatment of advanced melanoma patients with BRAF V600e mutations." (PMID 34113648, 2021). "Moreover, the 5-year update of CheckMate 067 demonstrated the long-term survival benefit of nivolumab groups in patients with BRAF-positive melanoma." (PMID 34914610, 2021). "Our proof of concept analysis on patients with advanced melanoma treated with BRAF/MEK inhibitor targeted therapy illustrates that maintaining a tolerable tumor burden may delay progression significantly." (PMID 33669315, 2021). "None of the nevus-associated melanomas had KIT mutation, and none of the melanomas harboring BRAF mutation carried a KIT mutation." (PMID 33648909, 2021). "•ASAH1 inhibitor blocks melanoma and enhances the effectiveness of BRAF inhibitor." (PMID 33766731, 2021). "Examining SIRT3 activators in BRAF inhibitor-resistant melanoma provided a model for how cancers with defective mitochondria, traditionally resistant to current therapies, may be targeted." (PMID 34831420, 2021). "A combination of PYK2 inhibitor with the BRAF inhibitor, vemurafenib, may therefore be an effective treatment for melanoma patients." (PMID 34570440, 2021). "In addition to BRAF mutant melanoma, enhanced mTORC1 activity has also been reported to associate with acquired resistance to combined inhibition of CDK4/6 and MEK in NRAS-mutant melanomas." (PMID 34304249, 2021). "This high phosphorylation capability of mutant BRaf, when couples with the mutant P16/INK4a as the result of cyclin-dependent kinase inhibitor 2A (CDKN2A) mutation or phosphatase and tensin homolog (PTEN) mutation, can lead to melanoma development." (PMID 33692796, 2021). "However, a recent study reported that both ALDH1A1 and ALDH1A3 correlated with favorable prognosis in metastatic BRAF wild-type and BRAF-mutant melanoma, respectively." (PMID 35048028, 2021). "In brain metastases from BRAF V600E melanoma, dabrafenib and vemurafenib, which are BRAF-inhibitors, have been extensively used, with intracranial response rates of 39.2% and 20%, respectively, with dabrafenib having a better brain distribution than vemurafenib." (PMID 34884457, 2021). "In other words, the therapeutic weaponry is more limited for patients with cutaneous melanoma lacking a BRAF mutation (about 50% of all cases) and for those with rare melanoma subtypes (e.g., uveal, acral, and mucosal)." (PMID 34073232, 2021). "Despite this, some prevalent mutated genes such as BRAF (50% of non-chronic sun damage melanomas) and NRAS (20-30%) have been identified." (PMID 33632214, 2021). "In all melanomas, real-time PCR did not disclose any BRAF mutation; melanoma #1 was KRAS and NRAS (lesions #2, 3, 4) wild type." (PMID 33614203, 2021). "Thus, the few available studies with real-world data showed positive achievements of targeted therapy for the cohort of BRAF-mutant melanoma patients." (PMID 34064013, 2021). "We next evaluated the concomitant BRN2 locus alterations, BRAF/NRAS mutations, and CDKN2A/PTEN alterations and found the most frequent genetic constellation that co-occurs with BRN2 loss in melanoma to be BRAFV600X mutation together with mono-allelic PTEN loss." (PMID 34140478, 2021).
melanoma (continued). "Interestingly, our lab recently showed that NRAS/BRAF-driven melanoma, pancreatic, or colorectal cancer cell lines increase a metabolic process, called autophagy, upon MEK1/2 inhibition, a process we will discuss in the following section." (PMID 34298710, 2021). "Likewise, in BRAF inhibitor-resistant melanoma, tumor cells were more reliant on glutamine as an alternate carbon source." (PMID 33804114, 2021). "Encorafenib is another FDA approved in the treatment of BRAF mutated melanomas and colorectal cancer, but no clinical data exists for its use in thyroid cancer." (PMID 34335481, 2021). "Importantly, downregulation of U34 enzymes in resistant melanoma cells can rescue the response to small molecule BRAF inhibitors." (PMID 33564819, 2021). "Targeting mutant BRAF in patients with melanomas harboring this oncogene has been highly successful as a first-line treatment, but other mutations may affect its efficacy and alter the route of acquired resistance resulting in recurrence and poor prognosis." (PMID 34282258, 2021). "These drugs elicit partial responses in NRAS-mutant melanoma, and in some BRAF-mutant cancers." (PMID 33367512, 2021). "Some studies mentioned that NRAS mutation seemed to be a poor prognosis in leptomeningeal melanosis and melanomas because of the activation of both ERK and the phosphatidylinositol 3-kinase (PI3K)/AKT pathway, in contrast to ERK signaling alone in BRAF mutation cases." (PMID 34063325, 2021). "In another study, PLX51107 slowed the growth of mouse BRAF V600E melanoma tumors by inducing the CD8+ T cell-mediated anti-tumor effects; moreover, PLX51107 proved to be an effective second-line therapy for CM tumors that harbored resistance to PD1/PDL1 checkpoint inhibition." (PMID 34575678, 2021). "This study indicates that phyto-sesquiterpene lactone derivatives may be useful in controlling highly metastatic, late stage BRAF mutant melanoma in humans." (PMID 33810045, 2021). "Moreover, the simultaneous presence of BRAF V600E mutation and loss of PHD2 expression in melanocytes led to their malignant transformation towards highly invasive melanoma." (PMID 33918883, 2021). "Notably, MCP-1, also considered as autocrine growth factor for melanoma and a metastasis-inducer, is produced by BRAF-resistant melanoma cells, and its plasma level was shown to increase in melanoma patients during BRAFi treatments." (PMID 33467521, 2021). "Ultimately, decisions about adjuvant therapy for resected stage III/IV BRAF mutant melanoma patients should be made on an individual basis, wherein the choice between adjuvant IT and TT takes into consideration potential toxicities, costs and patient preference." (PMID 33087895, 2021). "These include inhibitors specific for oncogenic BRAF V600 (BRAFi) and compounds targeting its downstream kinase MEK1/2 (MEKi), which particularly proved successful as a combination therapy for advanced melanoma, where BRAF V600 mutations make up ~50–60% of all cases." (PMID 34299213, 2021). "Our goal was to identify a candidate epigenetic regulator targeting drug that could effectively inhibit the growth of BRAF mutant melanoma cells." (PMID 34771678, 2021). "Finally, combined inhibition of autophagy and oncogenic BRAF induced cell death, which led to regression of established xenografted melanomas that were previously judged resistant to BRAFi alone." (PMID 34298710, 2021). "Although BRAFi improved the survival of patients with BRAF-mutated melanoma, its effect does not last long (a median time to progression of 5.1–8.8 months) due to the acquisition of drug resistance with multiple causes." (PMID 33478111, 2021). "With regard to melanoma, most currently available drugs inhibit BRAF and MAPK signaling." (PMID 34880267, 2021).
melanoma (continued). "Furthermore, patients with activating mutations in NRAS have a poorer prognosis, are refractory to BRAF inhibition, and exhibit a greater incidence of brain metastases than patients with either BRAF-mutant or BRAF/NRAS wild-type melanoma." (PMID 35187538, 2021). "Similarly, MEK inhibition in KRAS-mutant lung cancer A549 cells and BRAF inhibition in BRAF-mutant melanoma A375 cells also increased IRF1 and IFIT1 protein levels (right)." (PMID 34535668, 2021). "These responses are in contrast to those seen in other malignancies, such as melanoma, where in BRAF mutant cancer a combination of BRAF and MEK inhibition with immunotherapy has revolutionised treatment and led to survival for patients extending to a median of 2 years, from less than 9 months." (PMID 34298779, 2021). "We performed transcriptomic analysis of three different melanoma lines, two with BRAF and one with NRAS mutations, with or without AR silencing with two different lentiviruses." (PMID 33112375, 2021). "In melanoma treatment, ENF stops the signaling pathway of the V600E-mutated BRAF molecule." (PMID 34063139, 2021). "We found that miR-129-5p was most strongly induced after Vemurafenib treatment in parental BRAF mutated melanoma cells, but not in the corresponding BRAFi resistant cells, normal melanocytes or BRAF wildtype melanoma cells." (PMID 34063443, 2021). "For example, patients with BRAFV600E/K mutant melanoma may benefit from a short initial treatment with a BRAF/MEK inhibitor (e.g., 2 weeks) followed by checkpoint inhibitors." (PMID 34301276, 2021). "Furthermore, these effects were particularly evident in the A375R cell line, which exhibited resistance to dabrafenib, a mutated BRAF inhibitor, which opens up a new perspective for PARP-i use in the case of resistant melanoma treatment." (PMID 33572647, 2021). "BRAF kinase inhibitor can significantly inhibit the proliferation of melanoma cells with BRAF gene V600E mutations in the G1 phase but has no inhibitory effect on wild-type BRAF." (PMID 33622273, 2021). "The findings that a pan-PI3K inhibitor is effective as a single agent in most NZM cell lines lead us to investigate whether it would potentially be effective in melanomas that had become resistant to BRAF inhibitors." (PMID 33549048, 2021). "Melanoma tumors driven by BRAF mutations often do not respond to BRAF/MEK/ERK pathway inhibitors currently used in treatment." (PMID 33613844, 2021). "Notably, the YUMM3.3 murine melanoma with constitutively active BRAF (RAS binding independent) was sensitive to RGS treatment." (PMID 34092233, 2021). "An overactivated MAPK/AKT pathway is well-established in BRAF mutant melanoma." (PMID 33841154, 2021). "BRAF inhibitors have been developed and benefited melanoma patients." (PMID 33836681, 2021). "The five-year analysis of adjuvant dabrafenib and trametinib in patients with resected stage III BRAF V600-mutant melanoma confirmed the long-term benefit of the treatment with median RFS not being reached for dabrafenib and trametinib vs. 16.6 months in the placebo arm." (PMID 33435389, 2021). "A study presented at the 2019 ASCO Annual Meeting and conducted in institutions participating in the International Neoadjuvant Melanoma Consortium pooled data from six neoadjuvant systemic therapy trials (anti-PD-1 in 133 patients and BRAF/MEK target therapy in 55 patients)." (PMID 34178657, 2021). "The most frequent mutation found in around 90% of cases is V600 E. The discovery of vemurafenib (PLX4032) as a highly specific BRAFV600 E kinase inhibitor and its FDA-approval for treatment of BRAF mutant metastatic melanoma patients has changed the natural history of melanoma." (PMID 34068792, 2021). "Novel therapies targeting autophagy, which may promote cancer cell death in chemotherapy-resistant melanomas, are of great interest, especially for BRAF/NRAS wild-type melanomas." (PMID 34068618, 2021).
melanoma (continued). "Somatic mutations in genes encoding protein actors of this phosphorylation cascade constitutively activate the MAPK pathway: mutations in BRAF, neurofibromin 1 (NF1), NRAS, and c-KIT are the most frequent, representing 50, 20, 20, and 2% of melanomas, respectively." (PMID 33804655, 2021). "Here we report confirmatory data from the Phase II randomized open-label clinical trial comparing the antitumoral activity of the standard schedule versus an intermittent combination of vemurafenib (BRAFi) plus cobimetinib (MEKi) in advanced BRAF mutant melanoma patients (NCT02583516)." (PMID 34853302, 2021). "Vemurafenib, another BRAF inhibitor, can reverse the resistance that develops with the BRAFS365L mutation following dabrafenib combined with trametentinib treatment in melanoma, but none has been reported in NSCLC." (PMID 34178685, 2021). "Additionally, mutations in PI3K and AKT which lead to an hyperactivation of the pathway have been described to contribute to resistance to targeted therapy in BRAF melanomas." (PMID 34066022, 2021). "The next-generation sequencing of melanoma patient samples further demonstrated that 57% of the patients who frequented tanning salons harbored one of the BRAF mutations compared to 18% of the patients who had never used tanning salons." (PMID 34638397, 2021). "BRAF inhibitors have successfully been investigated in BRAF-mutant malignant melanoma." (PMID 33671873, 2021). "Many nevi and primary melanomas are polyclonal and contain cells with mutated BRAF and wild-type cells (without BRAF mutation)." (PMID 34203771, 2021). "BRAF mutations, particularly the V600E mutant, have not been linked to a substantial difference in patient survival compared to melanomas that do not contain this mutation." (PMID 35003391, 2021). "We next evaluated whether ASAH1 inhibition affects the sensitivity of melanoma cells to BRAF kinase inhibitors." (PMID 33766731, 2021). "In the case of melanomas, inducing pyroptosis with the DNA topoisomerase inhibitor etoposide could reduce tumor growth in BRAF inhibitor‐ and MEK inhibitor‐resistant melanomas." (PMID 34459122, 2021). "Despite the importance of the MAP kinase pathway in the treatment of melanoma, there is no consensus at which time point BRAF mutation testing should take place during the workup of melanoma." (PMID 34068774, 2021). "Additionally, targeted therapies approved for the treatment of BRAF V600–altered melanoma include BRAF inhibitors (dabrafenib, vemurafenib, encorafenib) and MEK inhibitors (trametinib, combimetinib, binimetinib)." (PMID 33687443, 2021). "Trametinib is an FDA-approved MEKi that has shown to be successful in treating melanoma with a BRAF V600E or V600K mutation; however, it is not clinically approved for RAS mutant cancers." (PMID 34830283, 2021). "In this study, we utilized the Flatiron Health database to retrospectively assess brain metastasis free survival (BMFS) from time of initiation of 1L therapy (immunotherapy, or targeted therapies) to metastasis or death in patients with advanced BRAF mutant melanoma." (PMID 34137219, 2021). "Moreover, TGFβ activates the AP-1 pathway leading the production of c-Jun and JunB, respectively in epidermal keratinocytes and dermal fibroblasts, known to be involved in the process of phenotype switching and BRAF inhibitor resistance in melanoma." (PMID 34604096, 2021). "IGF2BP1 inhibition increased the efficacy of BRAF and BRAF/MEK inhibitors in V600E-mutant melanoma, suggesting that this protein may serve as a therapeutic target." (PMID 33807778, 2021). "While both BRAF and NRAS are members of the MAPK pathway, melanoma tumors with these different mutations have divergences in terms of tumor aggressiveness, drug response, age of onset, and correlation with melanoma subtype." (PMID 35008307, 2021).